ABCC13 (ATP binding cassette subfamily C member 13 (pseudogene))
Synonyms: PRED6; C21orf73; ABCC13P
Gene: Transcribed unprocessed pseudogene on chromosome 21 (14,274,092 to 14,362,754, forward strand). Ensembl gene ENSG00000243064.
Diseases named in the same sentence as ABCC13 in open-access papers:
ABCC13 is named in the same sentence as 6 diseases in open-access papers, as found by Europe PMC text mining. Sharing a sentence is not in itself a finding about the gene and the disease. The quoted sentences say what the papers report.
breast carcinoma (1 paper, 2019). "It is reported that rs2822558/ABCC13 is related to breast cancer." (PMID 31888641, 2019).
colorectal cancer (1 paper, 2022). A primary or metastatic malignant neoplasm that affects the colon or rectum. "An example of upregulated DDPs was ABCC13, which exhibited remarkably a higher expression level in colorectal cancer than in normal adjacent tissue." (PMID 36348461, 2022).
dyslexia (1 paper, 2018). A learning disorder characterized by an impairment in processing written words. "However, it is worth noting that GWAS for dyslexia have been under‐powered so far and variants with the strongest association to dyslexia (e.g., in genes RBFOX2, ABCC13, ZNF385D, COL4A2 and FGF18) failed to survive genome‐wide statistical scrutiny." (PMID 30218584, 2018).
yellow fever (1 paper, 2023). "ABC transporter ABCC13 (AAEL023524) is downregulated in late dengue infection and overexpressed throughout yellow fever expression in vivo." (PMID 36971242, 2023).
cancer (2 papers, 2017 to 2022). A tumor composed of atypical neoplastic, often pleomorphic cells that invade other tissues. "Some cancer-specific lncRNAs, such as ABCC13, HOTAIR, LINC00472, and FER1L4 have also been reported to act as potential diagnostic and prognostic biomarkers in cancers." (PMID 29029488, 2017).
ABCC13 also shares sentences with these, for which no sentence is quoted: hepatocellular carcinoma (1 paper).